BCL2 (BCL2 apoptosis regulator)
Diseases named in the same sentence as BCL2 in open-access papers (continued):
Sharing a sentence is not in itself a finding about the gene and the disease.
breast carcinoma (continued). "A group of predicted BH3-only genes, found in the interactome of at least one Bcl-2 pro-survival protein, is highly down-regulated in all or most of the breast cancer subtypes compared to the normal samples." (PMID 31825969, 2019). "Breast cancer cells cotreated with genistein and radiation also exhibit upregulation of Bax and p73 and downregulation of Bcl2." (PMID 31618928, 2019). "In breast cancer, curcumin enhances mitomycin C sensitivity in breast cancer stem cells also by inducing Bcl-2 mediated apoptosis." (PMID 31308852, 2019). "Bcl-2 inhibition by ABT-199 treatment showed synergistic viability decreases when used in combination with doxorubicin in breast cancer, supporting the notion that Bcl-2 inhibition can sensitize cancer cells to chemotherapy." (PMID 31261935, 2019). "Breast cancer cells treated with curcumin show increased levels of pro-apoptotic protein Bax and decreased the expression of anti-apoptotic protein Bcl-2, resulting in an increase in ratio of Bax/Bcl-2." (PMID 31618928, 2019). "Intriguingly, we found a significant correlation between ∆Ψm collapse and deceased Bcl-2 following diosgenin treatment that led to an elevated level of activated caspases and promoted death of breast cancer cells." (PMID 31881805, 2019). "Lignans compound such as Vitexins isolated from seeds of Vitex Negundo induced apoptosis in breast cancer, ovarian cancer and prostate cancer cell lines by up-regulating Bax and down-regulating Bcl-2 protein." (PMID 31870094, 2019). "β-SDG inhibits the proliferation of breast cancer cells by elevating the levels of pro-apoptotic Bax and BCL2 associated agonist of cell death (Bad), and reducing the levels of anti-apoptotic Bcl-2 and Bcl-xl." (PMID 31126043, 2019). "In our study, Bcl-2 was frequently expressed in feline mammary carcinomas, as 72% of the cases expressed some kind of staining in the cytoplasm of tumor cells." (PMID 30630524, 2019). "There was significant co-expression of TFF3 with AKT1 (p = 0.0365), BCl2 (p = 0.0152), and NF Kappa-B (p = 0.0243) in breast carcinoma cases with residual carcinoma following neoadjuvant therapy which support the role of TFF3 in chemoresistance." (PMID 30744593, 2019). "We also aimed at investigating the prognostic significance of Bcl-2 expression in FMCs in order to evaluate its significance in the feline patient, and to compare with previous studies in human breast cancer." (PMID 30630524, 2019). "A consistent and strong positive correlation between Bcl-2 positivity and hormone receptor expression is reported in breast cancer, and concerns both ER and PR." (PMID 30630524, 2019). "DOX is known to induce apoptosis in breast cancer cells by reducing Bcl-2 expression as a traditional chemotherapy drug." (PMID 31242627, 2019). "In human breast cancer, the prognostic significance of Bcl-2 positivity in triple-negative carcinomas is controversial." (PMID 30630524, 2019). "BCL2 has been described as a favourable prognostic marker for all types of early-stage breast cancer." (PMID 30601841, 2019). "The objective of our study was to investigate Bcl-2 expression in a large cohort of feline mammary carcinomas, and to assess its relationship with other clinical and pathological features." (PMID 30630524, 2019). "In a further study, miR-15a and miR-16 expression was significantly downregulated in tamoxifen-resistant breast cancer cells and were able to enhance apoptosis via regulation of both Cyclin E1 and BCL2 expression." (PMID 35582270, 2019). "We explored the antitumor effects of BCL-2/BCL-XL inhibition using ABT-737 in a mouse model of Myc-driven breast cancer." (PMID 30728358, 2019).
breast carcinoma (continued). "BCL-2 is overexpressed in many cancers, including breast cancer as observed in our study, and contributes to tumor initiation, progression, and resistance to therapy." (PMID 31289309, 2019). "Very few papers reported Bcl2 as a possible partner of these bio-profiles, despite it was clearly demonstrated as a significant prognostic marker in breast cancer, and is part of the hormonal-related Oncotype Dx signature." (PMID 31158261, 2019). "A significant increase in Bcl-2 expression was previously observed in malignant mammary tumors, suggesting the evasion of apoptosis as one step in the progression to metastasis." (PMID 31676831, 2019). "Including BCL-2 expression in the scoring model increased the number of breast cancer cases in the cohort that were considered high certainty, effectively expanding the applicability of this technique to a greater proportion of patients." (PMID 30574014, 2018). "Regarding miR-34c, Achari and colleagues demonstrated that miR-34c exert tumour-suppressive effects in breast cancer through different mechanisms, such as induction of G2/M cell cycle arrest and suppression of the pro-survival factors BCL2 or SIRT1." (PMID 30533999, 2018). "We then highlighted that dual targeting of glycolysis, with 2-deoxy-D-glucose, and mitochondrial metabolism, using BCL2 inhibitors can be used as a potential strategy to stop the progression of both ER+ and TN breast cancer." (PMID 30255019, 2018). "Cruickshanks also demonstrated that anoikis-resistant breast cancer cells had multiple defects in their ability to undergo cell death processes, partly associated with increased expression of c-FLIP or protective BCL-2 proteins." (PMID 30305055, 2018). "In breast cancers, miR-195, miR-24-2, and miR-365-2 have been validated as negative regulators of BCL2 via their direct binding at its 3′ UTR." (PMID 29361709, 2018). "For example, in LAML, it is appreciated that BCL-2 expression levels predict sensitivity to BCL-2 inhibition, and recent studies in breast cancer imply that BCL-XL function is critical for sensitivity to MCL-1 inhibition." (PMID 30158527, 2018). "These lines of in vivo evidence suggest that Bcl-2 is a promising target in treating not only ER+ breast cancer but also TNBC." (PMID 29876007, 2018). "GLP induces apoptosis on MDA-MB-231 breast cancer cells by mitochondria-mediated intrinsic pathway promoting changes in the mitochondrial membrane potential and Bax/Bcl-2 ratio, cytochrome c release, and Caspases-3 and 9 activation." (PMID 30127738, 2018). "Previous studies on the effect of BCL2 proteins in breast cancer largely focused on individual members of the BCL2 network." (PMID 29352235, 2018). "Resveratrol significantly diminished growth of estrogen-positive breast cancer cells inducing apoptosis via reduction of Bcl2/BAX ratio." (PMID 29558948, 2018). "In vitro, XBP1s overexpression in an ESR1+ breast cancer cell line increased levels of the pro-survival protein BCL-2 and decreased mitochondrial membrane permeabilization when cells were challenged with the estrogen antagonist’s tamoxifen or fulvestrant." (PMID 30248920, 2018). "For example, nuclear localization of Bcl-2 and Bcl-xL was observed in various cancer cells including breast cancer, endometrial carcinoma, squamous cell carcinoma, and astrocytoma." (PMID 29497611, 2018).
breast carcinoma (continued). "Such heterogeneity can be explained by intrinsic differences in cellular BCL(X)L or BCL2 concentrations in breast cancer cell population, or by activation states of mitochondrial bioenergetics." (PMID 29899841, 2018). "Because BCL2 proteins are overexpressed in breast cancer and targetable by selective antagonists, we here analysed the effect of BCL2 and BCL(X)L selective inhibitors, Venetoclax and WEHI-539, on mitochondrial bioenergetics and cell death." (PMID 29899841, 2018). "Molecular studies have confirmed that miR-497 directly targets BCL2 and regulates apoptosis in breast cancer." (PMID 29361709, 2018). "The Bax/Bcl-2 ratio, as a candidate prognostic biomarker in breast cancer, indicates the degree of mitochondrial outer membrane permeabilization and, hence, cell entry for the execution phase of the apoptotic program." (PMID 29662002, 2018). "CHLO at a dose of 30 g/kg of chow significantly increased caspase-7 expression and Bax/Bcl-2 ratio in mammary carcinoma cells in rats." (PMID 30092754, 2018). "For MCF-7 breast cancer cells, data showed a significant decrease in the mRNA levels of BCL-2, KRAS and NRAS oncogenes and some of the YWHA family." (PMID 29444163, 2018). "The highest mRNA expression level in solid tumours were obtained for the Bcl-2 protein in breast carcinoma samples." (PMID 29515335, 2018). "It was reported that Adr treatment reduced the expression of anti-apoptotic Bcl-2 whereas increased the expression of pro-apoptotic Bax in breast cancer cells." (PMID 30039180, 2018). "Given that Bcl-2 is overexpressed in approximately 75% of breast cancers, this combination therapy appears promising." (PMID 29876007, 2018). "Strikingly, treatment of breast cancer cells with BCL2 and BCL(X)L selective inhibitors led to decreased mitochondrial network length." (PMID 29899841, 2018). "Lastly, in breast cancer specimens, miR-497 levels have been shown to be inversely correlated with BCL2 expression." (PMID 29361709, 2018). "It has been reported that targeting Bcl-2 with ABT-199 can increase therapeutic effects of tamoxifen on ER+ breast cancer in primary breast tumor xenograft models." (PMID 29876007, 2018). "It has been reported that HMGA1 plays anti-apoptotic role by modulating BCL2 in human breast carcinoma cells." (PMID 29581847, 2018). "In the next experiment, fruit peel polyphenols of Flavin7® showed significant increase in caspase-3 expression and Bax/Bcl-2 pro-apoptotic ratio in rat mammary tumor cells (30 g/kg of chow)." (PMID 30092754, 2018). "For instance, DIM induced apoptosis in MCF-7 and MDA-MB-231 breast cancer cells, by decreasing total transcript and protein levels of Bcl-2 and increasing Bax protein levels." (PMID 28698459, 2017). "Our previous study has suggested that TFF3 promotion of oncogenic behavior in breast cancer cells is BCL-2 dependent." (PMID 28445151, 2017). "Our experiment remarkably showed the pro‐apoptotic activities of high‐dose CLOs —it was characterized by an increase in the expression of caspase‐3 and Bax/Bcl‐2 ratio in rat mammary carcinomas." (PMID 28524540, 2017). "The expression levels of Bax and Bcl-2 in human breast cancer (MCF-7) cells after Cladosporol A treatement for 24 h were evaluated, using immunofluorescence microscopic studies and western blot analysis." (PMID 28728544, 2017). "There is an inverse correlation between Bcl-2 expression and chemosensitivity to chemotherapy drugs such as adriamycin and 5-fluorouracil (5-FU) in breast cancer cells." (PMID 28959140, 2017).
breast carcinoma (continued). "Western blot analysis and confocal microscopic analysis revealed that the expression of the two known miR-125a-5p negatively regulating pro-breast cancer cell survival molecules, Bcl-2 and HER2, is also increased in MCF7-TamC3 cells as compared to MCF7 cells." (PMID 29326587, 2017). "Compound 9f showed dose dependent inhibition of Bcl-2 in treated MCF-7 breast cancer cells as compared to untreated cells." (PMID 28814788, 2017). "The prosurvival protein Bcl-2, a key regulator of apoptosis in many types of human tumors, is positively regulated by miR-21, and an anti-miR-21 inhibitor downregulates Bcl-2 in breast cancer cells." (PMID 28744338, 2017). "For example, anti-apoptotic Bcl-2 expression is decreased in human breast cancer cell lines, MCF-7 and T47D with a silibinin treatment." (PMID 29112149, 2017). "Similar to our studies, anticancer properties of Sulforaphane were represented by the decreased Bcl-2 levels and increased caspase-3 activation in human breast cancer cells." (PMID 28808311, 2017). "Previous study showed that miR‐497 induced breast cancer cell apoptosis by negatively regulating Bcl‐2 protein expression." (PMID 28064447, 2017). "Further study shows that BTG1 functions as Bcl-2-regulated mediator and is involved in antisense Bcl-2-mediated cytotoxic effects in breast cancer cells." (PMID 27447746, 2017). "We evaluated the efficacy of curcumin in sensitizing chemotherapy drugs through regulation of Bcl-2-mediated apoptosis in breast cancer stem-like cells (BCSCs)." (PMID 28959140, 2017). "Bcl-2 has been described as antiapoptotic protein and plays important roles in regulating apoptosis in mammary epithelial cells and breast cancer cells." (PMID 29181403, 2017). "Previous studies showed that bcl-2 expression was inhibited by WWOX in breast cancer and bladder cancer, and that RUNX2 expression is up-regulated in WWOX-deficient mice." (PMID 28977834, 2017). "The result suggested that BTB extract induced the change in the expression of Bcl-2 family proteins, increasing pro-apoptotic Bax and decreasing anti-apoptotic Bcl-2, thereby increasing the likelyhood of apoptosis in breast cancer cell lines." (PMID 29086840, 2017). "In human breast cancer cells, berberine induces apoptosis through a mitochondrial dependent pathway by increasing the Bax/Bcl-2 protein ratio, activating caspases and inducing poly (ADP-ribose) polymerase (PARP) cleavage." (PMID 28702078, 2017). "Our new research showed Salvia officinalis L. induces apoptosis in mammary carcinoma cells through alteration of Bax to Bcl-2 ratio." (PMID 29387831, 2017). "Bcl-2 is localized to the mitochondrial outer membrane, and approximately 25%-50% of all primary breast cancers express high levels of Bcl-2." (PMID 29254147, 2017). "Some studies have showed that the expression of the Bcl-2 family proteins such as Bax, Bad and Bcl2 are closely related to the appearance and development of breast cancer." (PMID 28915591, 2017). "In all the three breast cancer cells, the ratio of Bax/Bcl-2 and cytosolic cytochrome c content increased significantly compared with control group." (PMID 28184196, 2017).
breast carcinoma (continued). "Immunohistochemistry results (mean ± standard deviation) of Bcl-2, Bax, and Bad expression in luminal epithelial cells of canine mammary tumors." (PMID 28081183, 2017). "In the present study, we observed positive correlation between HPV infection and higher BCL2 expression in breast cancers, with more detectable BCL2 protein in HPV-positive than HPV-negative breast carcinomas (50.0% versus 20.9%)." (PMID 29423411, 2017). "Over-expression of BCL-2 has been found in 60–80 % of breast carcinoma suggesting its role in breast cancer." (PMID 27658496, 2016). "Consistently with this idea, previous studies have shown that the IL-17RB/IL-17B signaling pathway promotes tumorigenicity and etoposide resistance in breast cancer cells through NFκB activation and Bcl-2 up-regulation." (PMID 27462789, 2016). "Conversely, TLK2 inhibition selectively inhibits the growth of TLK2-high breast cancer cells, downregulates ERα, BCL2 and SKP2, impairs G1/S cell cycle progression, induces apoptosis and significantly improves progression-free survival in vivo." (PMID 27694828, 2016). "ER plays a major role inthe tumorigenesis of breast cancer as it upregulates cyclin D1,Myc, Bcl-2 and VEGF (Vascular endothelial growth factor), whichplay a significant role in cell cycle, cell survival and thestimulation of angiogenesis." (PMID 28149048, 2016). "Recently, it was reported that MSM induced Bax protein expression in both MCF-7 and T47D breast cancer cell lines, and decreased Bcl-2 protein expression and suppressed hepatic tumor development through the activation of apoptosis." (PMID 27428957, 2016). "Bcl-2 binding to SLIRP was validated by co-immunoprecipitation and co-localization experiments both in lung cancer and breast cancer cell models forced to overexpress bcl-2 and in HL60 and HeLa cell lines, expressing the endogenous bcl-2 protein." (PMID 26866271, 2016). "This supports the idea that OHPg via PR-B/Bcl-2 axis drives breast cancer cellular senescence which follows an early autophagy mediated by Beclin-1." (PMID 27462784, 2016). "FGFR2 and BCL2 were again selected in this dataset confirming the strong relevance of the two genes in breast cancer." (PMID 27378931, 2016). "Emerging evidence indicates that mitochondrial clustering precedes cytochrome c release and an increase in the ratio of Bax/Bcl-2 during etoposide-, paclitaxel- or curcumin-induced apoptosis in breast cancer cells." (PMID 27418140, 2016). "To provide a mechanistic explanation of the inhibitory activities of Flavipin on breast cancer cells, we examined selected anti-apoptotic (Bcl2), adhesion (ITGA4) and pro-metastatic (Sox4) markers." (PMID 27907195, 2016). "SIRT1 inhibits breast cancer progression and accelerates the apoptosis of human breast cancer cell lines by downregulating the expression of pro-survival Bcl-2 protein." (PMID 26912776, 2016). "In sharp contrast, significant Bcl2 levels were detected in all CA TN breast cancer cells and remained relatively stable or even slightly increased upon NO exposure." (PMID 27473585, 2016). "On treatment with green tea polyphenols and EGCG, a significant reduction in cell growth associated with apoptotic changes, such as stimulation of BAX, cleavage of PARP, and down-regulation of Bcl-2, was observed in MD-MB-231 human breast cancer cells." (PMID 27657126, 2016). "The effect of metformin treatment on breast cancer cell viability and miR-26a, BCL-2, PTEN, MCL-1, EZH2, and MTDH modulation were evaluated." (PMID 27517917, 2016).